IL21 (interleukin 21)
Diseases named in the same sentence as IL21 in open-access papers (continued):
Sharing a sentence is not in itself a finding about the gene and the disease.
lung adenocarcinoma (7 papers, 2022 to 2025). A carcinoma that arises from the lung and is characterized by the presence of malignant glandular epithelial cells. "Mechanistically, Tfh cell-derived IL-21 was linked to enhancing CD8+ T cell function in mouse models of lung adenocarcinoma." (PMID 40351814, 2025). "In this context, we observed a positive correlation between the expression of IL-21 and the infiltrations of NK cells and T cells in both lung adenocarcinoma (LUAD) and lung squamous cell carcinoma (LUSC)." (PMID 38263004, 2024). "Recently, it was reported that in a lung adenocarcinoma mouse model, antigen-specific GC B cells interact with Tfh, which subsequently secretes IL-21 to promote anti-tumor CD8+ T cells." (PMID 35418862, 2022). "Previous studies showed that B cells can promote differentiation of tumor-specific CD4+ T follicular helper cells in a neoantigen-dependent manner, which in turn enhanced CD8+ T cell effector function through IL-21 production and drove anti-tumor immunity in a mouse lung adenocarcinoma model." (PMID 40519919, 2025). "Recently, it was report that T follicular helper cells producing IL-21 play crucial roles in lung adenocarcinoma, because these cells were able to induce the effect function of tumor-infiltrating CD8 via IL-21/IL-21R signaling." (PMID 35514957, 2022).
neuroblastoma (7 papers, 2011 to 2025). Neuroblastoma (NB) is the most common solid, extracranial childhood tumor. "The cytokines IFN-γ, IL-2, IL-7, IL-12, IL-15, IL-18, IL-21, and IL-27, promoted neuroblastoma regression via enhancing the efficacy of effector cells, whereas VEGF, IL-6, and IL-10 induced neuroblastoma progression through their immunosuppressive activities." (PMID 33322408, 2020). "The differential expression of AKT3, GNAI2, and IL21 was analyzed by comparing expression levels in murine neuroblastoma cells infected by the wild type RABV with control uninfected cells using RT-qPCR." (PMID 27872612, 2016). "Notably, IL-21-expanded NK cells may represent the latest improvement in the iterative process of developing an effective NK cell expansion protocol, showing efficacy in mouse models of neuroblastoma." (PMID 29456538, 2018). "In another syngeneic model, the combination of an anti-CD4 mAb with an IL-21-secerting neuroblastoma (NB) cell vaccine or rIL-21 induced potent CD8+ T cell responses and cooperatively cured most mice bearing systemic NB." (PMID 25961061, 2015).
systemic sclerosis (7 papers, 2011 to 2024). A chronic disorder, possibly autoimmune, marked by excessive production of collagen which results in hardening and thickening of body tissues. "Systemic sclerosis (SSc) patients have an increased frequency of CD21low B cells and of serum interleukin-4 (IL-4) and IL-21, each possible markers of joint involvement in inflammatory arthritis." (PMID 37763102, 2023). "In systemic scleroderma, such IFN gamma/IL-17A double-positive cells could be linked directly to fibrosis regulation through IL-21 release, and in PSC, expansion of IFN gamma coexpressing TH17 cells was observed after in vitro stimulation with bacterial antigens." (PMID 37256725, 2023). "In patients with systemic sclerosis (SSc), skin fibrosis could be effectively controlled under the treatment with anti-IL-21 and anti-ICOS antibodies." (PMID 39469708, 2024). "Interestingly, two previous studies reported that they were not able to detect IL-21 in the synovium of RA patients or the skin of systemic sclerosis patients." (PMID 22030011, 2011). "In addition, the epidermis of patients with systemic sclerosis expressed IL-21R (but not IL-21)." (PMID 22030011, 2011).
tuberculosis (7 papers, 2015 to 2024). A chronic, recurrent infection caused by the bacterium Mycobacterium tuberculosis. "The incorporation of IL-21 as an adjuvant in DNA vaccines has demonstrated substantial promise in augmenting immune responses against M. tuberculosis, underscoring the potential of IL-21 in enhancing the immunogenicity of tuberculosis DNA vaccines." (PMID 38793728, 2024). "This heightened response was comparable to the efficacy of BCG, indicating that IL-21 serves as a promising adjuvant to enhance the immunogenicity of tuberculosis DNA vaccines." (PMID 38793728, 2024). "Several clinical studies have detected changes in IL-21 production during active tuberculosis." (PMID 27819295, 2016). "However, little data exists characterizing the production and regulation of IL-21-expressing CD4+ T cells during tuberculosis." (PMID 26785168, 2016). "Taken together, our results demonstrated that MTB-specific IL-21+IFN-γ+CD4+ T cells from local sites of tuberculosis (TB) infection could be enhanced by IL-12, which have the features of both Tfh and Th1 cells and may have an important role in local immune responses against TB infection." (PMID 26785168, 2016). "In the present study, we found that after stimulation with M. tuberculosis antigens, NKT cells isolated from tuberculosis (TB) pleural fluid mononuclear cells (PFMCs) produced IL-21 and other cytokines including IFN-γ, TNF-α, IL-2 and IL-17." (PMID 26416419, 2015). "Pediatric TB was associated with elevated plasma transforming growth factor β (TGF-β), IL-21, and IL-23 levels, which suggested that these responses might play a crucial role in the pathogenesis of tuberculosis." (PMID 26416419, 2015). "In summary, we found that M. tuberculosis-specific antigens induced production of IL-21 in addition to IFN-γ, TNF-α, IL-2 and IL-17 by NKT cells in pleural fluids from TB patients." (PMID 26416419, 2015).
experimental autoimmune encephalomyelitis (6 papers, 2008 to 2026). An autoimmune demyelinating disease of the central nervous system that is produced experimentally in animals by the injection of homogenized brain or spinal cord in Freund's adjuvant. "The objective of this study was to elucidate the roles of T follicular helper and T follicular regulatory cells in the progression of experimental autoimmune encephalomyelitis and to assess their association with IL-21 expression and central nervous system tissue pathology." (PMID 41898758, 2026). "For instance, the administration of IL-21 before the induction of experimental autoimmune encephalomyelitis promotes the activation of T and NK cells in the periphery and contributes to the severity of the disease." (PMID 34488776, 2021). "Importantly, IL21 signaling is critical for induction of spontaneous experimental autoimmune encephalomyelitis." (PMID 30036399, 2018). "In study of spontaneous experimental autoimmune encephalomyelitis (EAE), IL-21 was observed to promote Th17 cell generation and enhance IL-23R expression on them, thus aggravated the inflammatory reaction and disease progression." (PMID 35693111, 2022).
fibrosis (6 papers, 2016 to 2024). the formation of excess fibrous connective tissue in an organ or tissue in a reparative or reactive process. "More importantly, our data indicated that IL-21 contributed to the formation and development of hepatic egg granuloma and subsequent fibrosis by driving GC responses and activating HSCs by immunohistochemical detection and blocking assay in vitro." (PMID 29192177, 2017). "Both IL-21 deficient and IL-21 receptor deficient mice developed pulmonary inflammation but no fibrosis upon bleomycin challenge, suggesting an important role of IL-21 in fibrogenic development." (PMID 32708044, 2020). "HCV-specific IL-21/ IL-17A responses did not correlate with microbial translocation or fibrosis." (PMID 27124305, 2016). "In our study, eight cytokines (CCL21, a T-cell chemoattractant, IL-9, IL-17F, IL-21, IL-28A, I-309, MIP-1β, and TARC) significantly correlated with BDG exposure in those without fibrosis, while only two cytokines (eotaxin-3 and M-CSF) were correlated in those with fibrosis." (PMID 39502781, 2024).
glioblastoma (6 papers, 2018 to 2025). The most malignant astrocytic tumor (WHO grade IV). "A recent study revealed that NK cells modified to express IL-21 maintained their anti-tumor activity against glioblastoma over time, whereas IL-15 armored NK cells were more prone to exhaustion after multiple tumor re-challenges." (PMID 40176196, 2025). "Unlike IL-15-expressing NK cells, which are translated into significant reductions in disease burden in preclinical models of glioblastoma, IL-21-expressing NK cells potently kill tumor cells." (PMID 40410571, 2025). "They compared 19 concentrations of cytokines (including IL-21) in the plasma of newly diagnosed glioblastoma patients and healthy patients using two different multiple immunoassay platforms." (PMID 37759505, 2023). "That is why IL-21, along with IL-2, IL-15 and mesothelin peptides, have been employed to evaluate humoral response using blood samples from patients with glioblastoma." (PMID 37759505, 2023). "The ability of IL-21 to influence the immune system can certainly be used to combat certain types of cancer, such as glioblastoma; however, few studies have evaluated the application of IL-21." (PMID 37759505, 2023). "Furthermore, the expression of IL-21, along with other cytokines, has been considered a marker for predicting the survival of a patient with glioblastoma." (PMID 37759505, 2023). "Also stimulating Vγ9Vδ2 T lymphocytes, the main peripheral γδ T cell, via IL-21, is effective in eliminating glioblastoma cells in an in vivo orthotopic model." (PMID 37759505, 2023). "Thus, this review’s purpose is to assess the molecular processes of IL-21, with a particular emphasis on the therapeutic potential of targeted treatments for the management of glioblastoma." (PMID 37759505, 2023). "Besides, interleukin-21 (IL21) increases the reactivity of allogeneic human Vγ9Vδ2 T cells against primary glioblastoma tumors." (PMID 36185204, 2022). "Importantly, these parameters were measured in NK cells cocultured with a glioblastoma cell line that was sensitive to NK cell lysis, and tumor-ligand binding is likely a key determinant of enhanced NK cell proliferation in the presence of IL-21." (PMID 40410571, 2025). "In the work of Zhenjiang and colleagues, the peripheral blood of patients with glioblastoma was analyzed (glioblastoma = 145; non-glioblastoma = 60) to measure the circulating T cells in the absence or presence of serum cytokines such as IL-2/IL-15/IL-21." (PMID 37759505, 2023).
graft versus host disease (6 papers, 2018 to 2025). An immune system disorder that occurs after allogeneic hematopoietic stem cell transplant and is a reaction of donor immune cells against host tissues. "In the graft-versus-host disease mice model, IL-21-neutralizing antibodies block the pathological progression of the disease by reducing skin fibrosis." (PMID 37628716, 2023). "Because NK expansion protocols frequently include factors such as high-dose IL-2, IL-15, and IL-21 that also stimulate proliferation of T cells, graft-versus-host disease is a particular concern." (PMID 29456538, 2018). "IL-21 neutralization is reported to prevent skin fibrosis in mice with graft-versus-host disease." (PMID 37628716, 2023). "Moreover, an ICOS+ Tfh-like cell subset contributed to dermal fibrosis via producing IL-21 in the skin of graft-versus-host disease (GVHD)-SSc mice." (PMID 32708044, 2020). "In the skin of graft-versus-host disease (GVHD)–SSc mice, increased ICOS+ Tfh-like cells promoted skin fibrosis in IL-21 and MMP-12–dependent manner." (PMID 35185577, 2022). "Even in the lack of CD8+ T cell–dependent graft-versus-host disease (GVHD) symptoms seen in hPBMC mice, highly activated Tph cells expressing CXCL13, IL-21, and IFN-γ infiltrated the salivary glands and induced severe reduction in saliva production." (PMID 41277554, 2025).
Hepatitis (6 papers, 2017 to 2023). Inflammation of the liver. "Hepatocytes infected with HBV produced exosomes containing miR-21, miR-192, miR-215, miR-221, and miR-222, and inhibited T cells’ secretion of IL-21, an important inflammatory molecule of hepatitis immunity." (PMID 37685904, 2023). "The combination of IL-12, IL-18, and IL-21 levels was more helpful to evaluate the degree of liver cell damage and predict the progression of hepatitis." (PMID 36383803, 2022). "Detection of IL-12, IL-18, and IL-21 levels was found to be helpful for evaluating the degree of liver cell damage and predicting the progression of hepatitis." (PMID 36383803, 2022). "In the immune clearance period, TGF-β synergizes with IL-6 or IL-21 to promote the differentiation of Th17 cells and liver inflammation." (PMID 30949222, 2019).
Hodgkins lymphoma (6 papers, 2019 to 2024). A heterogeneous group of malignant lymphoid neoplasms of B-cell origin characterized histologically by the presence of Hodgkin and Reed-Sternberg (HRS) cells in the vast majority of cases. "In addition, another study found that CXCR5+ICOS+CD8+ T cells show significant infiltration in tumor lymph nodes (LNs) of patients with Hodgkin’s lymphoma (HL) and could upregulate the expression of IL-2, IL-4, and IL-21, which promotes B-cell proliferation and antibody production." (PMID 38515134, 2024). "Similarly, previous studies have shown that IL-21 attracts regulatory T-cells via up-regulation of macrophage inflammatory protein-3α and protects cells from apoptosis via activation of STAT3 signaling pathways in IL-21R+ Hodgkin lymphoma cells." (PMID 30728806, 2019).
lupus nephritis (6 papers, 2019 to 2024). Glomerulonephritis in the context of systemic lupus erythematosus. "IL-21 has been linked to lupus nephritis due to its role in enhancing antibody production through T cell-dependent B cell stimulation." (PMID 39124778, 2024). "Previously, a single study associated IL-21 levels with lupus nephritis." (PMID 39124778, 2024). "Immune complexes depositing in the thyroid lead to immune cell infiltration (T and B lymphocytes) and cytokine release (INF‐γ, IL‐6, IL‐12, IL‐21, and IL‐17), like Lupus nephritis, which will exacerbate thyroid tissue damage." (PMID 34850456, 2022). "All this suggests that the IL-21 producing super-functional Th cells (IL-21+ IFN-γhi PD-1low Tmem cells) represent a novel Tfh-like subpopulation that can provide B-cell help in lupus nephritis mice in an IL-21- and CD40L-dependent manner." (PMID 32441253, 2020). "Induction therapy in patients with untreated lupus nephritis reduced the IL-21 levels." (PMID 39124778, 2024).
AIDS (5 papers, 2013 to 2019). A syndrome resulting from the acquired deficiency of cellular immunity caused by the human immunodeficiency virus (HIV). "While levels of IL-6 and TGF-β1 are relatively high during HIV and SIV infection, plasma IL-21 levels are diminished in AIDS patients." (PMID 29048384, 2017). "Thus, the pool of splenic Tfh cells expressing IL-21 is decreased during AIDS." (PMID 26640894, 2015).
allergic asthma (5 papers, 2019 to 2024). A asthma with a basis in a pathological type I hypersensitivity reaction. "Thus, IL-21 plays an important role in the pathogenesis of allergic asthma." (PMID 34867940, 2021). "Unlike allergic asthma associated with eosinophilia and Th2 cytokines, non-allergic asthma is often marked by neutrophil-dominated inflammation and the involvement of other T helper cell subsets, such as Th1 and Th17, which produce cytokines like IL-17, IL-21, and IL-22." (PMID 39664985, 2024). "Our study shows that DNT cell treatment significantly reduced the proportion of Tfh cells and decreased IL-21 secretion in OVA-induced allergic airway disease, which demonstrated the direct effects of DNT cells on ameliorating allergic asthma." (PMID 31534137, 2019). "Furthermore, several studies concerning the direct sensitization of HDM have indicated that various factors, such as IL-21 from CD4+ T cells, IL-33 from inflammatory monocytes, TLR4-dependent inflammation, and IRF3 signals, participate in mouse models of allergic asthma." (PMID 31616416, 2019).
autoimmune thyroid disease (5 papers, 2013 to 2024). Inflammatory disease of the thyroid gland due to autoimmune responses leading to lymphocytic infiltration of the gland. "Diarylpropionitrile, a specific agonist of ERβ and not of ERα, in vivo enhanced IL-17A, IL-21, and RORγt mRNA levels in splenocytes of experimental autoimmune thyroiditis model mice through binding of the agonist-activated ERβ to IL-17A and IL-21 gene promoters." (PMID 31547021, 2019). "Activated ERβ could directly bind to IL-17A and IL-21 gene promoters, and also indirectly promote IL-21 and RORγt gene transcription through interaction with NF-κB to stimulate the development of experimental autoimmune thyroiditis." (PMID 38730302, 2024).
B-cell lymphomas (5 papers, 2013 to 2025). "Moreover, Nlp deficient mice were prone to spontaneous B cell lymphoma, since the developments and functions of lymphocytes significantly depended on secretory proteins through ER-to-Golgi vesicle trafficking, including IL-13, IL-17 and IL-21." (PMID 38904019, 2024). "Results of preclinical studies presented here show that IL-21 is also an attractive candidate for combination with rituximab to treat B cell lymphomas." (PMID 23825648, 2013). "IL-21 has been evaluated as a monotherapy in early clinical trials for treatment of metastatic melanoma and renal cell carcinoma, and as a combination therapy with rituximab for non-Hodgkin B cell lymphomas (NHL)." (PMID 23825648, 2013). "αCD20-IL-21, a fusion protein comprising native human IL-21 fused to the NH2 terminal domain of anti-CD20, can directly induces apoptosis in B-cell lymphomas that were resistant to native IL-21 treatment." (PMID 39664443, 2024).
diffuse large B-cell lymphoma (5 papers, 2014 to 2023). "Previous findings indicate that STAT3 up-regulates c-Myc expression in IL21-treated diffuse large B-cell lymphoma." (PMID 26305332, 2015). "In the present study, the serum level of IL-21 and the expression of IL-21 on IL-21R with the pathogenesis of diffuse large B-cell lymphoma (DLBCL) was investigated." (PMID 24959288, 2014). "In the present study, the effect of IL-21 and IL-21R on the pathogenesis of diffuse large B-cell lymphoma (DLBCL) was investigated." (PMID 24959288, 2014). "Moreover, IL21 also mediates the apoptosis of various non-Hodgkin’s lymphomas, including follicular, mantle cell and diffuse large B-cell lymphoma." (PMID 26305332, 2015). "However, in more advanced malignancy stages, such as diffuse large B-cell lymphoma (DLBCL), IL-21 has been shown to exhibit anti-cancer activity by downregulating anti-apoptotic genes and promoting apoptosis, as well as growth arrest." (PMID 36765813, 2023).